CD7 (CD7 molecule)
Diseases named in the same sentence as CD7 in open-access papers (continued):
Sharing a sentence is not in itself a finding about the gene and the disease.
tumor (continued). "Thus, we speculate whether SECTM1 is an oncogene or a tumor suppressor dependent on the composition of immune cell types in the TIME, since multiple immune cells could express CD7, such as T cells, NK cells, and monocytes." (PMID 36818292, 2023). "Tumor immunophenotype was characterized by a strong expression of conventional myeloid antigens (CD13, CD33, CD15, MPO), although no monocytic (CD14, CD64, CD11c, CD11b, lysozyme), megakaryoblastic (CD61, CD41) and lymphoid (CD7, CD19, iCD79a, CD56, CD2) markers were found." (PMID 36980947, 2023). "Immunohistochemically neoplastic cells are typically CD3+, CD7+, CD103+, TCRβ+/− cells, CD4−, CD8−, and CD5−, mostly expressing CD30 with CD56 negativity, and demonstrate an activated cytotoxic phenotype (perforin+, granzyme B+, and TIA-1+), reflecting the origin of the tumor from cytotoxic IELs." (PMID 37627888, 2023). "Moreover, CD7-negative CD19-CAR-T cells also show enhanced anti-tumor activity compared to normal CD19-CAR-T cells." (PMID 36248810, 2022). "Similarly, circulating CD7+CD127+CD117+ ILCPs, could infiltrate the TME and locally differentiate into g1 ILCs, thereby leading to the enrichment of g1 ILCs in the tumor tissue." (PMID 36372017, 2022). "Although anti-CD7 CAR T cells were found to exhibit a good safety profile and achieve a high complete remission rate, the presence of CD7-negative tumor cells may lead to relapse." (PMID 35693763, 2022). "Tumor growth was monitored once a week by measuring the percentage of CD5 + /CD7 + tumor cells in the peripheral blood and by in vivo imaging to detect luciferase-expressing cells; for ethical reasons, mice were sacrificed when circulating CD5 + /CD7 + cells reached 40% of the total PBMC population." (PMID 30069011, 2018). "Compared to the NTR group, bioluminescence imaging (BLI) data indicated suppression of leukaemic cells on Day 7 after CD7 CAR-T injection in the CD7 CAR group followed by a rapid decrease in tumour burden, which could not be detected in mice of the CD7 CAR group at 22 days." (PMID 36517851, 2022). "Given the scarcity of truly tumor-specific antigens (absent on normal cells) and substantial tumor heterogeneity, pan-T-cell antigens (such as CD5 and CD7) have emerged as the predominant targets in clinical trials for T-cell malignancies." (PMID 41250215, 2025). "Case LYWS-1096 was a good example of the FL-like pattern; it comprised many tumor cells, positive for CD4 and strongly positive for TFH markers and negative for CD7." (PMID 37500795, 2023). "Distinct from T-ALL cells, the other tumor cells did not kill each other and still proliferated normally, although they have high expression of CD99 or CD7, the CAR-targeting antigen." (PMID 37112766, 2023). "CD5/CD7 bispecific CAR-T cells selectively killed tumor cells in a dose-dependent manner, but not CD5-CD7- Raji, demonstrating that CD5/CD7 bispecific CAR-T cells maintain good specificity." (PMID 35332132, 2022). "The immunophenotype of typical ATLL tumor cells is positive for CD3, CD4, CD5, CD25, CCR4, and CADM1, and negative for CD7 and CD8." (PMID 35625999, 2022). "Detailed analysis of Lin–CD7+ ILCs in PDAC and non-malignant pancreatic tissue revealed the presence of a largely tumor tissue-specific ILC population, characterized by the lack of conventional ILC marker CD127 and the expression of CD103, CD39 and CD45RO." (PMID 35793870, 2022). "Tumor cells in NKCL were consistently negative for CD3, CD4, and CD5 and showed moderate CD2, CD38, CD56, and CD94 and heterogeneous expressions of CD7, CD8, CD16, and CD26." (PMID 35299754, 2022). "Immunohistochemically, tumor cells are characterized by CD30, ALK, CD5, TIA-1, Granzyme B, EMA positive staining, and CD2, CD3, CD7, CD4, CD8, CD20, CD79a negative staining." (PMID 27612448, 2016). "In contrast to CD7, the role of natural killer cells (CD56+) as primary responders with an ability to recognize and lyse tumor cells without previous sensitization is well known." (PMID 20604962, 2010).
tumor (continued). "Additionally, as alternative effector cells lacking CD7 expression, NK cells were utilized to develop CD7-redirected CAR-NK cells, which exhibited significant tumor-killing activity." (PMID 38915099, 2024). "Immunohistochemically, the tumor cells are usually positive for pan-T-cell markers (CD2, CD3, CD5, and CD7), although one or several (particularly, CD5 or CD7) may be downregulated or absent." (PMID 36010351, 2022). "Briefly, tumor cells in AITL/FHTCL demonstrated a very characteristic immunophenotypic signature with positive expressions of CD2, CD4, CD5, CD45, and heterogeneous CD7 but negative expressions of surface CD3, CD8, CD16, CD56, CD25, CD26, and CD30." (PMID 35299754, 2022). "Bright expression of PD-1 was demonstrated on tumor cells in most cases other than diminished or absent CD3 and CD7 and it could clearly distinguish neoplastic T cells from normal/reactive CD4-positive T cells." (PMID 36160159, 2022). "Typically, tumor cells are CD2+, CD3+, CD4+, CD8−, CD5+, and CD25+, and CD7 is often negative." (PMID 34830926, 2021). "The tumor cells in ETTL-1 express CD3 and CD7, but not CD4, CD8, CD5, or CD56." (PMID 33457319, 2020). "Importantly, deletion of CD7 did not affect the short-term effector function of CAR T cells and enabled the expansion of functional CAR T cells with high anti-tumor activity." (PMID 30891427, 2019). "The amplification of genes such as COL5A1, IDO1, and GOLIM4 were in accordance with their higher expression in tumor samples, whereas no significant change of protein or phosphorylation levels was observed for genes with genomic amplification, such as CD4, CD7, LIME1, UNC93B1, C1S, C1R, or C8G." (PMID 34400640, 2021).
cancer (25 papers, 2016 to 2025). A tumor composed of atypical neoplastic, often pleomorphic cells that invade other tissues. "CD7/SIRα is an important innate immune checkpoint in cancer, and one study found that high SIRPA expression was associated with a favorable response to anti-PD-1 therapy, which explains the downregulation of SIRPA in the high-risk group." (PMID 40149637, 2025). "The activity profile of the K12 CAR-T reported here is in line with a previous published study, in which a second-generation ligand-based K12 (SECTM1) CAR-T cell eliminated cancer cells with high CD7 expression and secreted IFN-γ." (PMID 40589566, 2025). "Further, treatment of CD7-positive cancer cells with K12 CAR-T also triggered robust secretion of IFN-γ, with a spread in concentration from 6.1–22.5 ng/mL that correlated strongly with CD7 expression on cancer cells (R2 = 0.859)." (PMID 40589566, 2025). "An important issue in the use of anti-CD7 CAR-T cells against T-cell malignancies is the concept of “fratricide”, meaning the killing of therapeutic CAR-T cells by the CAR-T cells themselves due to shared expression of CD7." (PMID 38090582, 2023). "In conclusion, anti-CD7 CAR-T-cell therapy remains the most promising approach to T-cell malignancies." (PMID 38090582, 2023). "Currently, PersonGen BioTherapeutics is validating its CD7 CAR-γδ T cells in patients with R/R CD7+ T cell-derived malignant tumors in an early Phase I study (NCT04702841)." (PMID 35740670, 2022). "Importantly, progenies from both CD34+DNAM-1brightCXCR4+ and Lin-CD56-CD16+CD7- purified cells derived from cancer tissue, uninvolved tissue, and PBMC consistently expressed inhibiting NK cell receptors (KIRs and NKG2A)." (PMID 38390333, 2024). "Notably, cells of C8 subgroup were T cell-like cancer cells and expressed specific markers of T cells, such as CD7, CD3D, and CD3E." (PMID 36451812, 2022). "Notably, CD7 was identified in 40% of AML patients with poorly differentiated cancer, whereas TdT was found in 44%." (PMID 35350515, 2022). "A major difficulty of the development of CAR-T cells against T cell driven cancers is that the attractive antigens (such as CD7) are expressed on normal T cell surfaces as well, leading to potential fratricide of CAR-T cells (i.e., CAR-T cells attack each other due to the presence of CD7)." (PMID 36248810, 2022). "Although the available evidence indicates that SECTM1 is an immunostimulator and activates multiple immune cells via CD7-dependent manner, SECTM1 still has a cancer-promoting effect in tumors." (PMID 36818292, 2023). "Natural killer (NK) cells represent a subset of CD3- CD7+ CD56+/dim lymphocytes with cytotoxic and suppressor activity against virus-infected cells and cancer cells." (PMID 35087536, 2021). "Carefully analyzing of the shutdown-subnetwork of the TIC’s T cells suggests that CD7 and P4HB receptor subnetworks have been turned off by cancer cells." (PMID 29112124, 2017). "There are growing reports using nanobody-based immunotoxins to treat cancers by targeting a variety of antigens such as glypican-3, glypican-2, EGFR, HER2, VEGFR2, CD7 and CD38, which indicates the great potential of nanobody-based immunotoxins for cancer therapy." (PMID 36435809, 2022). "The phenotype of CTC-AT showed that the majority of sub- populations were characterized by the high expression of markers as CD44, CD90, CD105 and CD7 as well as elevated ALDH activity, thus suggesting the presence of cancer stem-like cells in CTC-AT population." (PMID 35820816, 2022). "Human T cells are genetically edited using CRISPR/Cas9 technology to remove both CD7 and the T-cell receptor (TCR) α chain (TRAC) to generate universal CAR-T cells (CD7 UCAR-T cells), which target cancer cells expressing CD7 without attacking the healthy T cells." (PMID 39620223, 2024). "Therefore, CD7-negative T cells may be an ideal source of CAR-T cells for T cell driven cancers and other hematological malignancies." (PMID 36248810, 2022).
cancer (continued). "In line with this, almost no residual CD7-positive cancer cells were detected after co-culture with K12 CAR-T cells, whereas the number of viable CD7-negative cancer cells was not affected compared to single cancer cell cultures." (PMID 40589566, 2025). "Besides CD7-negative CD7-CAR-T cells, naturally selected CD7-CAR (NS7CAR)-T cells may be another promising modification-free therapy against T cell driven cancers." (PMID 36248810, 2022).
hematologic malignancies (19 papers, 2021 to 2025). "CD7 encodes a transmembrane glycoprotein expressed mainly in T cells and natural killer cells, which plays an important role in the human immune system and is a potential therapeutic target for hematologic malignancies." (PMID 40825076, 2025). "CD7 chimeric antigen receptor T-cell (CAR-T cell) therapy is an emerging method for treating hematological malignancies, and is another breakthrough in CAR-T cell therapy." (PMID 39845313, 2024). "(2022) successfully administered allogeneic CAR-T cells to treat CD7-positive hematologic malignancies." (PMID 38799440, 2024). "More recently, an ”all in one” approach of sequential CD7-CAR-T followed by haploidentical alloSCT was evaluated in 10 patients with R/R CD7-positive hematologic malignancies." (PMID 39456582, 2024). "WU-CART-007 is an allogeneic CD7-directed, genetically modified, fratricide-resistant CAR-T cell product under development for treatment of CD7-positive hematologic malignancies." (PMID 39149468, 2024). "We can believe that CD7 CAR-T products play a significant role in the treatment of hematologic malignancies with high malignancy and limited treatment options." (PMID 39845313, 2024). "Our study confirms the clinical efficacy and safety of CD7 CAR-T cells in patients with hematologic malignancies through systematic review and meta-analysis." (PMID 39845313, 2024). "A phase I clinical trial was conducted to test genetically modified CD7-targeted allogeneic CAR-T cell therapy in hematologic malignancies." (PMID 39061100, 2024). "presented the results of a phase I clinical study investigating the safety, efficacy, and pharmacokinetics of genetically modified CD7-targeting allogeneic CAR-T cell therapy (RD13-01) in patients with R/R CD7-positive hematological malignancies." (PMID 37711206, 2023). "Early phase I clinical trial has been started in patients with relapsed and/or refractory T-cell hematologic malignancies using CD7 CAR-T cells with CD7 and TRAC knockout (NCT04264078)." (PMID 37193354, 2022). "CD7 is now famous for its wide application in the immunotherapy of hematological malignancies." (PMID 40761479, 2025). "The field of CAR-T cell therapy for hematological malignancies has been rapidly expanding, with researchers exploring various novel targets beyond the classical ones like CD19, BCMA, CD7, and CD30." (PMID 39061100, 2024). "Alternative CAR targets were explored in the treatment of hematological malignancies such as CD3, CD5, CD7, CD33, CD138, SLAMF7 and NKG2D ligands in pursuit of for more effective strategies." (PMID 39633491, 2024). "Studies have reported the activity of dual target CAR-T against T-lymphocyte hematologic malignancies, such as CD5/CD7 CAR-T cells." (PMID 39845313, 2024). "Recent Phase I results from a genetically modified CD7-targeting allogeneic CAR-T cell therapy (RD13-01) demonstrated encouraging efficacy and safety against relapsed/refractory CD7-positive hematological malignancies." (PMID 37798328, 2023). "T-cell immunophenotype was CD45+CD3dim+CD5-CD4-CD8+CD7+CD57p+CD25-CD30-, TCRγδ+, transducer and activator of transcripton-3 (STAT3) Y640F mutation and fusion gene NPL-DHX9 rearrangement were confirmed, which has never been reported in hematological diseases." (PMID 35600388, 2022).
infection (14 papers, 2013 to 2025). The state of being infected such as from the introduction of a foreign agent such as serum, vaccine, antigenic substance or organism. "CD5- and CD7-directed chimeric antigen receptor T-cell (5CAR and 7CAR) therapies for T-cell malignancies carry the risk of life-threatening infection." (PMID 41290542, 2025). "It is also worth exploring how to avoid and manage the risk of infection of CD7 CAR T-cells after treatment." (PMID 37215124, 2023). "p24+CD34+CD7+ cell counts significantly increased from week 1 to week 3 in association with a low average CD34+CD7+ cell count at week 1 after infection and a rapid increase of CD34+CD7+ cell counts at weeks 2–3." (PMID 30761146, 2019). "Among the ten patients who did not receive further treatment, three were in remission, three relapsed (including one with CD7-positive extramedullary disease), and four died of infection." (PMID 37711206, 2023). "Further assays and analyses revealed that CD34+CD7+CXCR4+ cells can be quickly depleted as early as 1 week after infection of the subset, and this was accompanied by the emergence of rare CD34+CD7+CD4+ cells." (PMID 30761146, 2019). "In addition, these infection-induced T cells displayed typical memory markers, including Cd7, and a resting cell signature, reflected by Jun, Fosb, Dusp1, and Dusp2 expression." (PMID 40240341, 2025). "On the other hand, however, as 63 have shown, CD7− T cells generated from CD7-depleted hematopoietic stem cells may contribute to maintaining T cell function and controlling infections." (PMID 37711206, 2023). "Therefore, CD5+CD7+ ILCs could act as sentinels, patrolling the body via the blood vessels, and migrate “on-demand” into tissue during infection and other immune challenges." (PMID 34867984, 2021). "In the ACE2-positive condition, overexpression of almost all cDNAs enhanced pseudovirus entry with CD7, EPHA4, LRCC8D, and LGMN overexpressing lines showing greater than 2-fold increases in Spike-mediated infection." (PMID 40674406, 2025). "The DEG analysis showed that LAIR2, CD7, KLRB1, TYROBP, TRAV19, TRAV21, and TRBV6-5 were upregulated in group E VS group B both breakthrough infection by BA.5.2." (PMID 39835127, 2024). "Therefore, vascular CD5+CD7+ ILCs may perform similar functions to blood monocytes that patrol blood vessels and gain access to tissue niches during altered organ homeostasis, when they differentiate into tissue-resident macrophages to support host defense against infection." (PMID 34867984, 2021). "Taken together, CD7+CD56negCD16+ and CD7+CD56+CD16+ NK cells are mature NK cell subsets with at least a fraction being terminally differentiated CD57+ NK cells; however, HIV-1-infection significantly alters the differentiation of both NK cell subsets." (PMID 24351015, 2013). "In the absence of CD7 gating we did not observe the expansion of CD56negCD16+ cells during early infection." (PMID 24351015, 2013). "CD7-negative relapse and infection are currently prominent problems in clinical data." (PMID 37215124, 2023). "Recently, single-cell RNA transcriptomic data revealed that emerging CD7-negative T cells expressed higher levels of T cell activation pathways than T cells before infusion, and monocyte reconstitution failure may account for severe infections (ChiCTR2200058969)." (PMID 39609714, 2024). "However, in contrast to early infection, CD16 expression did not appear to differ significantly on CD7+CD56+CD16+ or CD7+CD56negCD16+ NK cell subsets in chronically HIV-1-infected subjects compared to healthy controls (right half)." (PMID 24351015, 2013). "Regarding CXCR4 expression levels in different subsets, the frequencies of CD34+CD7+CXCR4+ cells in HIV+ samples (mean 2.08 ± 2.56%) were significantly reduced compared to those in HIV− samples (mean 2.49 ± 2.42%), regardless of the degree of infection (data not shown)." (PMID 30761146, 2019).
blood cancers (2 papers, 2023 to 2026). "Conversely, blood cancers consistently reach ORRs of 70–90% with CD19- or CD7-targeted CAR-T cells, including an 89% ORR in CD19-positive B-cell malignancies and 87% complete remission in CD7-targeted T-cell malignancies." (PMID 41559435, 2026). "In this process, nucleotide bases in donor cells are edited so that the gene for CD7 (a genetic marker in blood cancers) is changed from cytosine to thymine, thus producing a ‘stop codon’ that terminates the production of CD7." (PMID 38550949, 2023).
CD7 also shares sentences with these, for which no sentence is quoted: multiple myeloma (7 papers); cutaneous T-cell lymphoma (4); erythroderma (3); rheumatoid arthritis (3); anaplastic large cell lymphoma (2); B-cell acute lymphoblastic leukemia (2); brain tumors (2); lung adenocarcinoma (2); non-Hodgkin lymphoma (2); psoriasis (2); tuberculosis (2); acute promyelocytic leukemia (1); Alzheimer disease (1); Anxiety (1); Ascites (1); Atrophy (1); attention deficit-hyperactivity disorder (1); autoimmune enteropathy (1); bladder cancers (1); brain disorder (1); breast (1); carotid atherosclerosis (1); colon tumor (1); colorectal carcinoma (1); congenital syphilis (1); cranial nerve neuropathies (1); depression (1); dermatitis (1); eczema (1); endometrial cancer (1).
A further 39 diseases each share a sentence with CD7 in 1 paper.